AQP3 (aquaporin 3 (Gill blood group))
Diseases named in the same sentence as AQP3 in open-access papers (continued):
Sharing a sentence is not in itself a finding about the gene and the disease.
cancer (continued). "Increasing evidence suggests that the water/glycerol channel aquaporin-3 (AQP3) plays a pivotal role in cancer metastasis." (PMID 28991174, 2017). "Immunochistochemical analysis of AQP3 expression in the cancer tissues of patients with ER-positive breast cancer." (PMID 26219409, 2015). "When endogenous AQP3 was inhibited, the number of cancer cells migrating through matrigel was significantly decreased compared with the untreated group, while AQP3 over-expression had the opposite effect (P < 0.05)." (PMID 24887009, 2014). "When AQP3 was initially identified as putative drug target, limited information was available on the role of this protein family in cancer." (PMID 23017148, 2012). "RNAi assays in this study showed that knockdown of AQP3 attenuated the H. pylori-induced proliferation and migration of cancer cells." (PMID 23152856, 2012). "In addition to their transport activity, the overexpression of AQP1, AQP3 and AQP5 in cancer has been associated with signal transduction pathways and cytoskeleton reorganization, resembling mechanisms typically mediated by receptors." (PMID 39941100, 2025). "AQP3 has emerged as a key oncogenic factor across multiple cancers." (PMID 40806720, 2025). "Altogether, the in vitro and in vivo data suggested that MP06 was partially associated with cancer stemness and EMT in H1299 cells and that suppressing AQP3 expression to target VEGF may be an effective anti-angiogenic therapy." (PMID 39611488, 2025). "Based on the involvement of AQP3 in the modulation of cell viability and cancer progression through the modulation of the EMT process, these data propose that MOMAST®, beyond its antioxidant ability, can modulate other intracellular signaling affecting cell survival." (PMID 39857360, 2024). "Furthermore, AQP3 knockdown prevented the metastasis of breast orthotropic xenographs to the lungs in vivo, backing up the function of AQP3 in cancer metastasis." (PMID 38336645, 2024). "It was suggested that AQP3 may be a factor limiting the therapeutic action of 5′-DFUR, because of AQP3-deletion lowered the drug’s effectiveness - making it a possible chemotherapeutic target in the development of a cancer therapy combination approach." (PMID 38336645, 2024). "In summary, the present study proved that AQP3 functioned as an oncogene and might serve as a promising target for cancer therapy." (PMID 38463942, 2024). "Nevertheless, it is well established that AQP3 is upregulated in different cancers." (PMID 39857360, 2024). "The authors suggested that AQP3 may be part of the cellular response to oxidative stress, since in cancer cell lines, increased AQP3 expression was accompanied by increased migratory capacity and increased cell viability." (PMID 38785550, 2024). "A recent study demonstrated that arsenic could induce the autophagy of keratinocytes via enhancing the expression of AQP3, suggesting a novel role of AQP3 in mediating the uptake of As, which in turn leads to cancerous skin lesions." (PMID 37719549, 2023). "Therefore, we further investigated the correlation of AQP3 with the PI3K/Akt pathway which was reported as dysregulated in cancer." (PMID 37175840, 2023). "Overall, several AQPs, including AQP1, AQP3, AQP4, AQP5, AQP8, and AQP9, have been suggested to transport H2O2, and their expression promotes cancer cell growth and migration, However, solid data exist only for AQP3- mediated H2O2 transport as one of the key mechanisms for cancer cell migration." (PMID 35847914, 2022). "In addition to transporting water and glycerol, it can also transport H2O2, an important second messenger in cellular activities, which makes the role of AQP3 in cancer more significant." (PMID 35972604, 2022). "AQP3 can interact with certain chemotherapy drugs or participate in certain cancer treatments." (PMID 35972604, 2022).
cancer (continued). "Of note, at least four AQPs (AQP1, AQP3, AQP4, and AQP9) have been shown to modulate the activity of specific MMPs, which appears to be a key mechanism underlying the promotion of cellular local invasion and cancer cell metastasis by AQPs." (PMID 35847914, 2022). "Interestingly, being under-represented in TNBC cells, AQP3 played a more important role in CAP-induced anti-cancer efficacies than AQP1 that was over-expressed in these cells." (PMID 35637961, 2022). "Overall, our present study revealed that the LINC00659/miR-370/AQP3 axis contributes to GC progression, which may provide clues for the exploration of cancer biomarkers and therapeutic targets for GC." (PMID 35957833, 2022). "In addition, AQP3 was involved in the EGF-induced ERK pathway in cancer, in which AQP3-mediated H2O2 modulated SHP2, an indispensable part of the downstream MAPK signaling cascade." (PMID 35972604, 2022). "Recently, an increasing number of researchers have pointed out that AQP3 is inclined to be of considerable importance in cancer development, which indicates that it may serve as a biomarker of cancer prognosis." (PMID 35972604, 2022). "In addition, AQP3 upregulation by estrogen in estrogen receptor-positive breast cancer and by both estrogen and progesterone in endometrial cells, affected cancer cell migration and invasion through reorganization of actin cytoskeleton and EMT." (PMID 35187089, 2022). "Likewise, AQP3 can regulate the malignant behaviors of cancer cells through several signaling pathways." (PMID 35972604, 2022). "AQP3 protein was observed in the cytoplasmic membrane of cancer tissue in 82% of lung samples." (PMID 36233821, 2022). "Also, more research is needed to find out the mechanism of AQP3 overexpression that accelerates cancer progression." (PMID 33993193, 2021). "AQP3 also may be contributed to ATP generation energizing cancer cells to proliferate and develop tumor." (PMID 34681181, 2021). "Considering that gold compounds affect both AQP3 and AQP7, this POT may be advantageous as a drug candidate for AQP3-overexpressing cancers." (PMID 32252345, 2020). "AQPs and, in particular, the AQP3 isoform are well known to be involved in cancer biology." (PMID 32252345, 2020). "Also, many descriptive studies have shown positive correlations between AQP3 expression and cancer progression and prognosis." (PMID 33168815, 2020). "Glycerol-permeable AQP3 in other tissues is involved in nutrient uptake and metabolism, and it could contribute similarly in some cancers." (PMID 32679804, 2020). "Likewise, overexpressed AQP3 increases the MMPs (matrix-metalloproteases), which further promote the cancer cell invasiveness." (PMID 32351935, 2020). "Moreover, the AQP3-mediated transport of H2O2 through the plasma membrane likely plays a pivotal role in cancer progression." (PMID 30893772, 2019). "This merits more research into the importance of AQP3-facilitated glycerol transport in cancer invasiveness, and whether gold-based compounds such as auphen can also be used to suppress cancer invasion and metastasis." (PMID 29922644, 2018). "In addition, AQP3 plays a role in cancer cell invasion and in aggravation of epithelial-to-mesenchymal transition." (PMID 30042691, 2018). "All of these classes also have been linked with cancer cell migration; however, H2O2 transport has thus far been linked only to AQP3 as a control mechanism in cancer cell migration." (PMID 29922644, 2018). "In addition to AQP3, AQPs 1, 4, 5, and 9 also have been linked to EMT in different types of cancer cells." (PMID 29922644, 2018). "AQP3 has been suggested to increase EGF-induced cancer growth and migration by mediating H2O2 flux." (PMID 29922644, 2018). "The involvement of AQP3 in H2O2 entry and the related cell signaling in cancer cells suggest that AQP3 may represent a new potential therapeutic target for cancer treatment." (PMID 29292793, 2017).
cancer (continued). "Thus, the mechanisms underlying regulation of EMT by AQP3 overexpression is an important future research topic to unravel the role of AQP3 in cancer." (PMID 28991174, 2017). "Observations from cell cultures suggest that AQP3 promotes cancer cell proliferation." (PMID 28991174, 2017). "In addition, AQP3 knockdown abrogated metastasis to lungs from mammary orthotopic xenographs in vivo, supporting the role of AQP3 in cancer metastasis." (PMID 28991174, 2017). "Several studies show that AQP3 may also contribute to cancer progression by increasing the motility and invasiveness of cancer cells." (PMID 28991174, 2017). "We found that AQP3 was up-regulated, and E-cadherin was repressed in cancer tissues." (PMID 24887009, 2014). "In this context, we cannot exclude that inhibition of AQP3 might influence the biological effects of the compounds towards cancer cells, although other studies need to be performed to validate such a hypothesis." (PMID 22624030, 2012). "Here, we examined whether up-regulation of aquaporin 3 (AQP3) mRNA in cancer cells treated with 5′-DFUR represents a collateral transcriptomic effect of the drug, or conversely, AQP3 participates in the activity of genotoxic agents." (PMID 23017148, 2012). "Interestingly, the anticancer drug, curcumin, down-regulates AQP3 expression in cancer ovarian cells via a mechanism that involves, at least partially, inhibition of the EGFR pathway and downstream AKT." (PMID 23017148, 2012). "AQP1 has previously been shown to be involved in cell cycle control, suggesting that AQP3 may also have a role in the progression of cancer." (PMID 16001974, 2005). "Considering the number of studies reporting the consistent implication of AQP1, AQP3 and AQP5 in the development of multiple cancer types and their strong association with signaling pathways, this review is focused on the critical roles of these AQPs as transceptors involved in cancer progression." (PMID 39941100, 2025). "However, it remains unclear whether AQP3-dependent glycerol and/or H2O2 transport is associated with metabolic disorders and cancer progression." (PMID 39857360, 2024). "Therefore, targeting AQP3 is trusted to have great potential for cancer treatments." (PMID 36983077, 2023). "Furthermore, AQP3 may indirectly contribute to the oxidative resistance of the SUM159PT cancer cell line, prompting future studies to investigate AQP3 regulation of cancer stress resistance." (PMID 37175840, 2023). "Additionally, several studies show that AQP3 may also contribute to cancer progression by increasing the motility and invasiveness of cancer cells." (PMID 36983077, 2023). "In addition, increased levels of AQP3 expression have been found in many cancers, and increased AQP3 expression enhances the proliferation, invasion, and migration of cancer cells and exacerbates the epithelial–mesenchymal transition-mediated cancer progression." (PMID 37143707, 2023). "Moreover, HIF-1α could be upregulated by ROS transported by AQP3, which made a difference in reprogramming cancer metabolism." (PMID 35972604, 2022). "However, whether the AQP3-dependent glycerol transport correlates with metabolic disorders and cancer progression remains to be better clarified." (PMID 35874817, 2022). "Consequently, AQP3 would not represent a specific indicator of benign or malignant neoplasms, thus limiting its use as a diagnostic marker." (PMID 32075009, 2020). "Currently, the most well-characterized role of AQP3 is the promotion of cancer metastasis, for AQP3 is abnormally escalated in various kinds of cancers and knockdown of the AQP3 gene could significantly decrease cell proliferation, and increase cell death or apoptosis in cancer cells." (PMID 32331274, 2020). "It will be interesting to investigate whether AQP3 promotes EMT in these cancers." (PMID 29922644, 2018). "Evidence implicates that overexpression of AQP3 may aggravate EMT of cancer cells." (PMID 28991174, 2017).
cancer (continued). "This review explores the pivotal roles of AQP1, AQP3 and AQP5 as transceptors in cancer biology, underscoring their importance as pharmacological targets." (PMID 39941100, 2025). "Significant progress has been made via the development of anti-AQP antibodies and via the encapsulation of AQP3 inhibitors such as Cuphen and ST004 in liposomal formulations designed to target cancer tissues." (PMID 39941100, 2025). "We assessed cell viability, intracellular ROS, changes in AQP3 and AQP5, and key antioxidative and cancer-related pathways (NRF2, PI3K/AKT, FOXOs)." (PMID 40244097, 2025). "This review focuses on the pivotal roles of aquaporins AQP1, AQP3 and AQP5 in tumor biology, emphasizing their significant contributions to cancer progression." (PMID 39941100, 2025). "Inhibition of AQP3 expression can reduce H2O2 inflows induced by growth factors and weaken the signal cascade in cancer cells." (PMID 38230207, 2024). "Rubenwolf and colleagues researched with Muscle-invasive bladder cancer and showed that high AQP3 expression was related with significantly enhanced PFS and cancer-specific survival (CSS)." (PMID 38336645, 2024). "Nevertheless, knockdown of AQP3 in pancreatic BXPC3 and HPAFII cancer cells reduced cell growth and spread." (PMID 38336645, 2024). "In this model, AQP5 showed a highly efficient peroxiporin activity compared to AQP3, revealing the major role of AQP5 in the dynamic fine-tuning of the endogenous concentration of H2O2 and possibly an influence on cancer initiation and progression." (PMID 39125952, 2024). "Our results suggest that AQP3 modulates PI3K/Akt activation and oxidative response in cancer cells, and that this modulation is cell-line-specific." (PMID 37175840, 2023). "Further research is warranted to untangle the influence of AQP3 and AQP5 expression in the biophysical properties of cancer cells." (PMID 35455986, 2022). "So far, studies of AQP1, AQP3, and AQP5 involvements in many different cancer types are performed on the basis of numerous cell line, in vivo mice model, and expression profiles of these AQPs in resected cancer tissue samples." (PMID 35847914, 2022). "AQP3, induced by EGF, can promote growth and cellular migration of various cancer cell lines through promoting H2O2 flux, which itself can trigger cell proliferation and migration." (PMID 35847914, 2022). "The suppression of AQP3 expression reduces EGF-induced H2O2 influx and attenuates EGF signaling cascades in various cancer cells." (PMID 35847914, 2022). "Protein or mRNA expression levels of AQP3 are related to the TNM stage, lymph node status, relapse, metastasis, and some other clinical indicators, which ultimately contribute to cancer outcomes." (PMID 35972604, 2022). "This work, for the first time, attributed the anti-cancer efficacy of CAP to its selectivity against cancer stemness, and proposed the AQP3/SCAF11/FOXO1 axis in mediating this process." (PMID 35637961, 2022). "The results show that AQP3 is required for EGF-induced cell signaling and cancer progression by a mechanism involving EGF-induced generation of extracellular H2O2, and its intracellular transport by AQP3." (PMID 30893772, 2019). "We detect spatial proximity of areas consisting of apparent cancer glands (“FOSB-enriched”), inflammation (“AQP3-enriched”) and reactive stroma (“NR4A1-enriched”)." (PMID 29925878, 2018). "In summary, for the first time, we demonstrated that AQP3 increases CD44 expression through Wnt/GSK-3β/β-catenin signaling pathway and promotes the stem-like properties of cancer cells in GC." (PMID 26918728, 2016). "Thus, AQP3 up-regulation is not a collateral effect of nucleoside-derived drug action, but may be implicated in the ability of some cancer cells to respond to treatment." (PMID 23017148, 2012). "Multivariate Cox regression analysis was used to assess the value of AQP3 tumour expression with regard to recurrence-free (RFS), progression-free (PFS) and cancer-specific survival (CSS)." (PMID 23043286, 2012).
cancer (continued). "A few studies have suggested that AQP5 is involved in promoting epithelial-to-mesenchymal transition (EMT), a key step in cancer metastasis, and that transforming growth factor-β (TGF-β)-induced EMT modulates AQP3 expression supporting tumor invasion and the establishment of metastatic niches." (PMID 40305202, 2025). "Moreover, in various cancers, AQPs such as AQP1, AQP3, and AQP5 exhibit correlated expression, reinforcing their significance in tumor progression." (PMID 40725460, 2025). "We first investigated the correlation between AQP3 expression and survival in HCC cancer patients." (PMID 38463942, 2024). "Moreover, AQP3 is located near the H2O2-producing NADPH oxidase 2 (NOX2) and transports H2O2 produced by NOX2 into the cancer cells." (PMID 37175840, 2023). "Finally, our results imply that AQP3 can modulate PI3K/Akt activation and oxidative response in a cancer-cell-line-specific manner." (PMID 37175840, 2023). "Induced expression of AQP3 in response to EGF in colorectal, gastric, and pancreatic cancer cell lines can enhance activities leading to the aggressiveness of growing cancer cells, including increased cell migration, invasion, and metastasis with mesenchymal transformation." (PMID 35847914, 2022). "In this study, we focused on the role of AQP3 and AQP5 because most of the studies demonstrated that these AQPs were significantly increased and played prominent roles in the proliferation, migration, and angiogenesis of cancer." (PMID 35741021, 2022). "We report AQP3-5K K48-ubiquitination via SCAF11 with AQP3-19F phosphorylation being essential, and demonstrate synergies between CAP and Atorvastatin towards enhanced anti-cancer efficacy." (PMID 35637961, 2022). "Based on our findings, we have concluded that combinatorial treatment by CXCR4-ligand modified L1-polyplexes formed with AQP3, CDC20, and COL4A2 siRNAs effectively inhibits proliferation of TNBC cells and can be suggested as useful tool for RNAi-mediated cancer therapy." (PMID 34681181, 2021). "We next investigated whether AQP3 could transport extracellular H2O2 into naive macrophages, as was found in keratinocytes, epithelial cells, and cancer cells." (PMID 33168815, 2020). "Indeed, AQP1 induces angiogenesis, AQP3 stimulates cellular migration, proliferation or invasion, AQP5 expression correlates to cancer proliferation and migration, and AQP5 and AQP9 regulate chemotherapy resistance." (PMID 32630469, 2020). "The expression of AQP3 is stimulated by hormones that are commonly increased in cancer, such as EGF and estrogens, but how overexpressed AQP3 accelerates cancer progression is not clear." (PMID 30893772, 2019). "Knockdown of AQP3 in human esophageal and oral squamous cell carcinoma with siRNA correlated with reduced phosphorylation of FAK, impaired cell adhesion and cell death; these effects would be predicted to impair cancer cell migration." (PMID 29922644, 2018). "Aquaporin 3 (AQP3) plays a vital role in carcinogenesis and cancer progression." (PMID 30072625, 2018). "In addition, miR-874 is involved in tumor progression by suppressing the protein levels of MMP-2 and uPA and targeting E2F3, HDAC1, AQP3 STAT3 and HCA587/MAGE-C2 in a variety of cancers." (PMID 28525377, 2017). "It is also not clear how overexpressed or ectopically expressed AQP3 accelerates cancer progression." (PMID 28991174, 2017). "Although our earlier studies showed that AQP3 promotes EMT, whether this protein promoted the stem-like properties of cancer cells in GC remained unknown." (PMID 26918728, 2016). "Vimentin immunoactivity was observed in 14 carcinoma tissues where AQP3 was overexpressed and E-cadherin was lacking." (PMID 24887009, 2014). "Positive signals for nuclear vimentin were detected in 15.7% (14/89) of cases, with vimentin only expressed in carcinoma tissues that over-expressed AQP3 and lacked expression of E-cadherin." (PMID 24887009, 2014).